AKT1 (AKT serine/threonine kinase 1)
Diseases named in the same sentence as AKT1 in open-access papers (continued):
Sharing a sentence is not in itself a finding about the gene and the disease.
breast cancer (continued). "Together, these results support the rationale for combining treatment with STINGa and AKT1 inhibitors in endocrine‐resistant breast cancer, but not endocrine‐sensitive breast cancer." (PMID 39023171, 2024). "Furthermore, we analyzed the prognostic value of combining p‐AKT1 and nuclear IRF3 protein levels in ER+ HER2– breast cancer patients." (PMID 39023171, 2024). "The lack of SENP3 can lead to an increase of AKT1 SUMOylation, thereby regulating the polarization of macrophages towards the M2 subtype, promoting the progression of breast cancer." (PMID 39314848, 2024). "Capivasertib and Ipatasertib are oral AKT inhibitors that target all three isoforms of AKT (AKT1, AKT2, and AKT3), inhibiting downstream signaling pathways that promote tumor growth and the survival of breast cancer cells." (PMID 39274207, 2024). "Inducible ablation of Akt1 in mammary epithelium after mammary tumors were formed inhibited tumor growth but not metastasis." (PMID 38722955, 2024). "Notably, CXCR4 has been identified as the therapeutic target of Balixafortide, whereas AKT1 as the therapeutic target of Capivasertib and Ipatasertib, all of which have been subjected to rigorous scrutiny in phase III clinical trials for breast cancer." (PMID 38887235, 2024). "In the context of brain metastasis in breast cancer, a previous study by our group showed that overexpression of PTEN in the brain-seeking cell line MDA-MB-231BR reduced tumor cell migration, via suppression of specifically AKT1 activity." (PMID 37483521, 2023). "Knowing that the phosphoinositide 3-kinase/Akt1 signaling pathway has emerged as a target for breast cancer therapy, it is no surprise that the inhibition of Akt1 warrants special attention." (PMID 37504472, 2023). "Our analysis showed that only AKT1 and MMP9 were significantly upregulated in breast cancer tissues compared to normal tissues, suggesting that they may be the most promising targets for follow-up research." (PMID 37165049, 2023). "We identified an increased presence of phosphoproteins such as p-AKT1, p-STAT3, p-SMAD3, p-CREB1, p-p38, p-PTN11, and p-ERK1 in mammary tumors compared to the mammary gland, which should be further investigated as potential novel biomarkers in mammary carcinogenesis." (PMID 37568820, 2023). "GC-MS and LC-MS analyses identified 31 and 16 components, respectively, of which selected compounds were used to evaluate the interaction between key receptors (AKT-1, COX-2, and HER-2) of breast cancer based on binding energy (ΔG) and inhibition constant (Ki)." (PMID 37894581, 2023). "miRNAs are one of the first set of molecules proposed to promote EMT in the absence of Akt1 expression in a breast cancer study." (PMID 35406397, 2022). "Differential expression of AKT1 and RPS6KB2 by race warrants further investigation to elucidate their roles in racial disparities of treatment resistance and outcomes between Black and White women with breast cancer." (PMID 35608730, 2022). "This is to prevent AKT1 from forming HER2-driven mammary tumor by suppressing negative feedback of RTK signaling." (PMID 36286049, 2022). "Unlike Akt1, Akt2 does not induce paladin phosphorylation and fails to inhibit breast cancer cell migration, instead it promotes breast cancer cell migration." (PMID 36180910, 2022). "On the other hand, Tranilast decreases growth and differentiation of some cancerous cells, including prostate cancer cells (CU 145, PC3, (LNcap) by increasing phosphorylation of AKT1 and decreasing the phosphorylation of ERK1 / 2 as well as G1/S cell cycle arrest in murine breast cancer cell line." (PMID 34452560, 2021).
breast cancer (continued). "Systemic Akt1 deletion inhibited lung metastases whereas systemic Akt2 deletion enhanced mammary tumorigenesis and metastasis at least in HER2-enriched and luminal B mouse models of breast cancer." (PMID 34298660, 2021). "Another study demonstrates that the presence of PIK3CA/AKT1 mutations and absence of alterations in MTOR or TSC1 were associated with sensitivity to capivasertib monotherapy in HER2− breast cancer." (PMID 34419139, 2021). "THSWD could regulated the RNA and protein expression of core targets HRAS, MAPK1, AKT1, GRB2, and MAPK14 for treatment of breast cancer." (PMID 34513708, 2021). "Palladin, an actin-associated protein, was identified as a specific substrate for Akt1 and not Akt2 and was shown to inhibit Akt1-mediated cell migration in breast cancer cells." (PMID 34298660, 2021). "When the study was designed, AKT1 mutation was reported in only 1–4% of oestrogen receptor-positive breast cancers;1, 2 thus AKT1 testing was not part of the original protocol." (PMID 32035020, 2020). "In vitro, downregulation of AKT2, but not AKT1 or AKT3, attenuated cell proliferation and 3D spheroid growth in PTEN-deficient prostate and breast cancer cells." (PMID 33276499, 2020). "To confirm previous observations of the effect of LASP1 knockdown on AKT1 phosphorylation, we performed experiments with MDAMB-231 and MCF-7 breast cancer cells, stably transfected with doxycycline-inducible LASP1-specific shRNA, transiently transfected with different LASP1-specific siRNAs." (PMID 32075106, 2020). "It showed that Ursolic acid could bind to AKT1/VEGFA, then inhibited breast cancer growth through ErbB or Estrogen pathway." (PMID 32978480, 2020). "Based on the previous data showing a LASP1-mediated PI3K/AKT1 activation and our own findings demonstrating overexpression of LASP1 in breast cancer cells and in CML, we wanted to address whether there is a direct regulation of AKT1 by LASP1 in these cells." (PMID 32075106, 2020). "In addition to AKT3, AKT2 has also been found to have tumour suppressive functions in certain tissues as shown in two separate mouse models of breast cancer, where AKT2 deletion accelerated tumour development while AKT1 deletion inhibited tumour growth." (PMID 32453400, 2020). "The investigation of AKT isoform expression and activation in human breast cancer probes and breast cancer cell lines detected expression of AKT1 and AKT2 in all breast cancer cell lineages with a higher abundance in the luminal breast cancer subtype." (PMID 31752925, 2019). "In contrast to our result, Akt1 but not Akt2 was found to modulate the expression of Cyclin D1 in lung and breast cancer cells." (PMID 31252679, 2019). "Thus, TRIB3 consistently reduced the phosphorylation of AKT1, a kinase that can interact with FOXO1 25, indicating that the AKT-FOXO1 interaction plays a critical role in TRIB3-enhanced breast cancer stemness." (PMID 31844113, 2019). "In opposition to the studies confirming distinct roles of AKT1 and AKT2 in cell proliferation and tumor growth, Watson and Moorehead attribute AKT1 knockdown as well as AKT2 knockdown to a suppressing effect on tumor initiation and growth of an IGF1R-positive breast cancer mouse model." (PMID 31752925, 2019). "This suggests that upregulation of Akt1 and simultaneously downregulation of COX2, as observed in our data set, may actually be beneficial in breast cancer." (PMID 31921382, 2019). "In contrast to the distinct functions of AKT1 and AKT2 in breast cancer, both isoforms exhibit a decreasing effect on migration, invasion and focal adhesion by inhibiting the activity of β1-integrin in prostate cancer cells which are also highly hormone-dependent like breast cancer cells." (PMID 31752925, 2019). "AKT1 mediates this effect through a negative regulation of receptor tyrosine kinases like EGFR, whereas AKT2 is a suppressor of the pro-migratory miR-200 family like in breast cancer cells." (PMID 31752925, 2019).
breast cancer (continued). "In addition, AKT1 mediates the pro-proliferative and pro-survival signals of estrogen and IGF-1 on breast cancer cells." (PMID 31752925, 2019). "Furthermore, resveratrol induced β-TrCP-mediated TWIST1 degradation to attenuate AKT inhibitor MK-2206-induced EMT in breast cancer and that AKT1/PKBα serves as a negative regulator of EMT and breast cancer metastasis." (PMID 31547193, 2019). "A couple of studies confirmed the anti-metastatic and anti-migratory ability of AKT1 independent of the breast cancer subtype." (PMID 31752925, 2019). "In order to further confirm that β-catenin nuclear accumulation was stimulated by EGFR signal in Akt1-impaired cells, we tested the effect of Gefitinib, an inhibitor of EGFR tyrosine kinase on the β-catenin nuclear accumulation in the breast cancer cells treated with Akt1 siRNA." (PMID 30445978, 2018). "Additionally, TiHo-0906 cells at low and high passage also displayed CNGs in regions harbouring other known breast cancer-related genes like FOXO3 and MYB (FCA B2), AKT1 (FCA B3), and GATA-3, CCND2, CDK4 and PFDN5 (FCA B4)." (PMID 30185896, 2018). "Our results suggested that Flag-PIKfyve WT but not a S318A mutant PIKfyve binds to Akt1, confirming that Akt1 phosphorylates PIKfyve at Ser318 site in breast cancer cells." (PMID 30445978, 2018). "Certainly, in our breast cancer model, impairment of Akt1 or Akt2 does not produce identical biochemical profiles, as indicated by the effect on important proteins, such as Survivin or β-catenin." (PMID 29518912, 2018). "This study revealed that amplification of Akt3 but not of Akt2 or Akt1 can be detected in diverse cancers, e.g., glioblastoma, melanoma, ovarian and breast cancer." (PMID 29562639, 2018). "The stringent up-regulation of SGK1 in response to progesterone led to an activation of a tumor metastasis suppressor gene, NDRG1, via a set of AP-1 network genes to inactivate AKT1, ERK1/2, and EGFR kinases, impeding the invasion and migration of breast cancer cells." (PMID 30337371, 2018). "Given that Akt1 inhibition promotes the activation of EGFR in breast cancer cells, we further examined whether the inhibitor of EGFR tyrosine kinase Gefitinib could suppress breast cancer metastasis induced by Akt1 inhibitor." (PMID 30445978, 2018). "Inhibition of Akt1 using MK2206 could induce an increase in the expression of EGFR and β-catenin in breast cancer cells." (PMID 30445978, 2018). "In conclusion, AKT1 and AKT2 level might be used as biomarkers of breast cancer progression early in the diagnosis process to discriminate which subset of patients could progress sooner and consequently have potentially worse clinical outcomes." (PMID 28287129, 2017). "Our results show that AKT1 and AKT2 isoforms regulate breast cancer cells differently." (PMID 28287129, 2017). "We reviewed the functional properties of the driver nodes found to have the highest impact in controlling the essential proteins; they are ERBB2, SRC, PDPK1, PRKDC, mTOR for breast cancer, ERBB2, AKT1, GSK3B, ABL1 in pancreatic cancer, and RET in ovarian cancer." (PMID 28871116, 2017). "The results of MAPK antibody array showed that SAHA and TRAIL DR5 could affect the activity of AKT1, AKT2, and TOR protein in breast cancer cells." (PMID 29018571, 2017).
breast cancer (continued). "In the non-responder MDA-MB-231 breast cancer cell line, knockdown of Akt1 by shRNA led to a significant increase in residual DNA-DSBs after irradiation with 2 Gy and with 4 Gy." (PMID 27137757, 2016). "To date, no studies have examined the capacity of AKT1(E17K) to drive mammary cancer in a genetically engineered mouse model." (PMID 27004402, 2016). "Moreover, Oct3/4 was revealed to maintain the survival of CSC-like cells of Lewis lung carcinoma 3LL cells and breast cancer MCF7 cells, partly by inhibiting apoptosis through the Oct4/Tcl1/Akt1 pathway." (PMID 26483189, 2015). "PIK3CA, AKT1, PTEN and Ki67 status across a collection of 77 matched ER+ breast cancers." (PMID 24520381, 2014). "Functional analysis of large scale breast cancer sequencing studies identified six non-hotspot AKT1 pleckstrin homology domain mutants." (PMID 25277176, 2014). "Disruption of Akt1 or Akt2 did not affect cell morphology or the expression of luminal or basal cytokeratins in mammary tumors." (PMID 23919516, 2013). "We have performed functional analysis of six non-hotspot AKT1 pleckstrin homology domain mutants identified in recent large-scale breast cancer sequencing studies." (PMID 23237847, 2013). "Despite the absence of Akt1 or Akt2, mammary tumors that developed in the MTB-IGFIR mice maintained detectable levels of phosphorylated Akt." (PMID 23919516, 2013). "Therefore, we sought to explore the relationship between activation and compartmentalization of Akt1 and Akt2 and the outcome of targeted therapy in a sample of patients with metastatic HER2-positive breast cancer treated with trastuzumab." (PMID 22842582, 2012). "Because BRCA1 is the most frequently mutated gene in hereditary breast cancers, the relationship between AKT1 and BRCA1 could constitute the missing molecular link between sporadic and familial breast cancers." (PMID 21321378, 2010). "Another study in 402 ERα-positive breast cancer patients showed clearly that cytoplasmic Akt1 and Akt3, but not Akt2, expression was correlated significantly with pAkt expression." (PMID 18184439, 2008). "An immunohistochemical analysis of human breast cancers revealed that lack of Akt1 phosphorylation correlates with low HIF-1α levels." (PMID 19384426, 2007). "Recombinant Akt1 failed to phosphorylate a p27 mutant lacking this site, and in some breast cancer cell lines Akt1 hyperactivation altered p27 location." (PMID 16780593, 2006). "However, the combination of SVIL‐AS1 and p‐AKT1 did not predict the outcomes of breast cancer patients better than SVIL‐AS1 alone, indicating that SVIL‐AS1 is a potent biomarker of patient outcome." (PMID 40135844, 2025). "However, recent study demonstrated that both breast-specific Akt1 and Akt2 deletion impaired breast cancer development driven by ErbB2 overexpression, but breast cancer metastasis was not affected by breast-specific Akt1 deletion." (PMID 36180910, 2022). "Moreover, the results suggest that specific Akt1 inhibition inhibits breast cancer metastasis regardless of the origin of the primary tumor." (PMID 35578699, 2021). "Based on next-generation sequencing analysis, genetic alteration in Akt1 (E17K and other pathologic mutations) was significantly enriched in metastatic breast cancer compared to primary breast cancer and Akt1, but not Akt2 or Akt3, was identified as an actionable target." (PMID 34298660, 2021).
breast cancer (continued). "However, the cell lineage may affect the pharmacologic sensitivity to Akt1/2 inhibition, for instance, PIK3CA-mutant breast cancer cell lines are more sensitive than PIK3CA-mutant colon cancer cell lines." (PMID 33916378, 2021). "Also, no mutations were detected for other described breast cancer‐associated genes (e.g., RAD51, RAD50, p27, ESR1/2, ERBB2, ERBB3, AKT1, CCDN1, FGFR1, MYC, and RB1) in any of the tissues or the CTC cell line." (PMID 32667137, 2020). "In addition, tissue-specific overexpression of constitutively active Akt1 accelerates breast cancer development induced by Erb2/Neu or PyMT but does not change the frequency of lung metastases." (PMID 33110146, 2020). "Together with the previous results, we conclude that EDNRB, particularly EDNRB-442, regulates AKT1 activation in some, but not all, breast cancer cells, and that this effect may also be present in other cancer types such as kidney cancer." (PMID 32201539, 2020). "However, we did not detect any changes of Wnt ligands in breast cancer cells treated with Akt1 siRNA." (PMID 30445978, 2018). "Interestingly, we note that the knockdown of Akt1 did not induce the upregulation of EGFR mRNA expression in breast cancer cells, suggesting that the upregulation of EGFR is a transcription independent regulation." (PMID 30445978, 2018). "In this study, we discovered that knockdown of Akt1 induced β-catenin nuclear accumulation in breast cancer cells, while inhibition of β-catenin nuclear accumulation using XAV-939 could reverse Akt1 knockdown-induced breast cancer invasion." (PMID 30445978, 2018). "In PC-3 prostate cancer cells, siRNA-mediated knockdown of AKT1 inhibited cell migration and cell adhesion, whereas AKT2 knockdown promoted cell migration suggesting that AKT1 has a pro- and AKT2 has an antimigratory role in prostate cancer, in contrast with their functions in breast cancer." (PMID 28082369, 2017). "Based on the results shown here, our prediction is that PI3K, panAKT or specific AKT1 inhibition may not be recommended, and may even be contraindicated in breast cancer, as it might promote tumor invasiveness and cancer dissemination." (PMID 28287129, 2017). "Finally, we provide clinical data demonstrating that increased AKT1 gene expression 24 hours after epirubicin exposure characterizes ER positive, but not ER negative, primary breast cancers that subsequently regress on anthracycline treatment." (PMID 28476032, 2017). "Similarly, regulation of a number of AKT isoform-specific downstream effectors have been identified, including the degradation of nuclear factor of activated T cells (NFAT) mediated by AKT1 and up-regulation of β1-integrin by AKT2 that regulates breast cancer cell migration." (PMID 28082369, 2017). "Similarly, Arboleda and colleagues showed that AKT2 overexpression promoted adhesion and invasion in human breast cancer cell lines, whereas AKT1 overexpression did not." (PMID 28513565, 2017). "In addition, combination of MMTV-driven AKT1(E17K) with MMTV-HER2 overexpression prevents HER2-driven mammary tumor formation, in part through negative feedback inhibition of RTK signaling mediated by AKT1(E17K)." (PMID 27004402, 2016). "Moreover, AKT1(E17K) prevents HER2-driven mammary tumor formation, in part through negative feedback inhibition of RTK signaling." (PMID 27004402, 2016). "Akt1 was reported to be able to trans-activate Slug expression to promote EMT progression in breast cancer and melanoma cells, but no data revealed whether Slug could regulate Akt1." (PMID 27036045, 2016). "Additionally, rapamycin-induced PI3K-dependent Akt1 activity and a lack of radiosensitization were concurrently observed in the breast cancer cell line MDA-MB-231." (PMID 27137757, 2016). "This may imply that targeting GAB1 or IRS1, but not AKT1, might be a better targeted strategy for breast cancer treatment." (PMID 25569504, 2015).